MYC (MYC proto-oncogene, bHLH transcription factor)
Diseases named in the same sentence as MYC in open-access papers (continued):
Sharing a sentence is not in itself a finding about the gene and the disease.
tumor (continued). "Therefore epigenetic factors and E2F and MYC are clearly involved not only in the tumor initiation but also in the recurrence development." (PMID 31316092, 2019). "Both LMP2A/λ-MYC/p27Super and λ-MYC/p27Super mice displayed dramatically delayed tumor onset." (PMID 30992353, 2019). "Comparison of the MYC status in two original tumor and adjacent tissue samples and their explant derivatives demonstrated that PDEc culture conditions preserve their original tumor sample-specific nuclear MYC status." (PMID 30728358, 2019). "Gene expression levels measured relative to the adjacent normal cortex sample revealed numerous oncogenic driver genes with >2-fold higher expression in the tumour and clone samples, including genes encoding AURKA/B, CDK4/6, FGFR1, AKT1/2, MTOR, MET, PIK3C2A, WNT5A, SFRP4, and MYC." (PMID 30736342, 2019). "Oxidative and oncogenic stresses in MYC overexpressed tumours will induce DNA damage." (PMID 30746633, 2019). "Understanding the molecular mechanisms how tumor cell-specific DNA (hydroxy)methylation patterns are established and maintained by MYC may provide novel therapeutic strategies, aiming at specific components of the DNA (de)methylating machinery." (PMID 31266538, 2019). "MYC, a transcription factor governing a large number of gene expressions, plays a vital role in tumorigenesis through its multiple effects on tumor cells, typically by controlling cell proliferation and survival, and elevated expression of MYC was found in approximately 70%of human cancers." (PMID 31258527, 2019). "Further, we assessed the protein levels of p‐AKT and c‐MYC in tumor xenograft tissues." (PMID 31397502, 2019). "HACER allows for ready exploration of diverse tumor-specific enhancers that regulate the MYC gene." (PMID 30247654, 2019). "Over the past 30 years, MYC has attracted the attention of a large number of cancer scientists, virus experts, biochemists and geneticists for its role in promoting proliferation, progression, chemoresistance, angiogenesis and tumor metastasis." (PMID 30866868, 2019). "Thus, while our model system further supports the concept of using PLK1 inhibitors to target MYC-driven tumours, important next steps will be testing this mechanism in more clinically relevant contexts." (PMID 31455158, 2019). "Colon cancer associated transcript 2 (CCAT2), a newly discovered lncRNA located at a recurrently amplified region (8q24) in cancers, was demonstrated to promote tumor growth, metastasis, and chromosomal instability in colon cancer via upregulation of the proto-oncogene, MYC." (PMID 31398859, 2019). "However, much remains elusive how 5mC and 5hmC patterns contribute to the deregulation of gene expression during MYC-driven tumorigenesis and tumor maintenance." (PMID 31266538, 2019). "Therefore, we propose that the amplification of SUPT5H enables tumor cells to escape MYC-driven apoptosis." (PMID 30928206, 2019). "Therefore, ATR overexpression in MYC overexpressed tumours will be expected to promote proliferation and aggressive phenotypes." (PMID 30746633, 2019). "Thus, the MYC-miR-105-MXI1-MYC-signaling axis-mediated metabolic reprogramming of stromal cells contributes to a sustained tumor growth by conditioning the shared metabolic environment." (PMID 31281797, 2019). "Both of these observations support the notion of larger, more metabolically active tumours being more susceptible to necrosis, irrespective of MYC status." (PMID 31028445, 2019). "MYC rearrangement, tumour necrosis (necrosisPET) and parameters derived from semiquantitative analysis of 18F-FDG PET are fundamentally linked to metabolism, yet the relationship between these factors remains unknown." (PMID 31028445, 2019). "By carrying out a comprehensive genome-wide DNA (hydroxy)methylation analysis, we show that cellular senescence and tumor regression upon MYC inactivation in a mouse model of T-ALL (EμSRα-tTAα;tet-o-MYC) is associated with genome-wide changes in 5mC and 5hmC patterns." (PMID 31266538, 2019).
tumor (continued). "However, the exact mechanistic role of MYC as a sensitizer of AMPK-mediated tumor apoptosis remains to be clarified." (PMID 30728358, 2019). "Conversely, proteins that were significantly more abundant in the B-raf V600E_high samples were clearly related to the proliferative nature of these tumors (and poor prognosis) and include several known oncogenes tumor drivers, e.g., the transcription factor MYC, and the growth factor HDGF." (PMID 31835364, 2019). "LMP2A/λ-MYC/p27Super mice and λ-MYC/p27Super mice both displayed dramatic delays in tumor onset." (PMID 30992353, 2019). "Since MYC amplification is a common phenomenon in patients with GC, it is reasonable to infer that those genes may also be overexpressed in the tumor tissues of patients." (PMID 31645899, 2019). "As too high MYC levels are potentially dangerous for cancer cells, targeting of MYC by miR‐17‐5p may be a means to maintain optimal MYC levels and sustain continuous tumor growth." (PMID 30451365, 2019). "Although both PVT1 and MYC coexist in 8q24, are amplified in many tumor types and are both highly upregulated in our EAC patient-cohort, we found that upregulation of PVT1 is highly associated with advanced stage and poor prognosis, while MYC expression was less relevant to poor survival." (PMID 31601234, 2019). "However, that RNAi-mediated knockdown of MYC combined with JQ1 led to additive anti-tumor activity in PC3 and DU145 cells, demonstrates MYC’s importance to growth of these JQ1-resistant cells." (PMID 30846826, 2019). "As a result, USP28 is required for c-MYC-mediated tumor cell proliferation." (PMID 29415985, 2018). "MYC is therefore considered as one of the most important drivers of tumor development and has been highlighted as a key therapeutic target for cancer therapy for a number of tumor types." (PMID 29968736, 2018). "When taken together, the 12 different pathways we found under MYC control for gastric carcinogenesis represent many biological functions, meaning that MYC overexpression in GC disturbs almost all the regular cellular processes in favor of tumor development." (PMID 30410872, 2018). "Thus, a combined suppression of MYC-induced apoptosis and MYC-driven proliferative signals supports extensive tumor development." (PMID 29371588, 2018). "An implication of this is that irrespectively of whether different ways of targeting the spliceosome have anti-tumour activity through divergent downstream mechanisms c-MYC could act as a common sensitizer by increasing the extent of alterations in splicing." (PMID 29796170, 2018). "MYC amplification was associated with HER2 status (p = 0.01) and tumor size (p = 0.01)." (PMID 29523126, 2018). "Therefore, it is probable that only the tumor cell populations with c-MYC amplification or copy number gain underwent complete response to chemotherapy, and the residual tumor showed no amplification or copy number gain." (PMID 30420657, 2018). "MYC expression was also verified to be highly expressed in tumor tissues (P < 0.01)." (PMID 30378283, 2018). "Among these genes, MYC is a well-known oncogene that plays an important role in tumor progression." (PMID 30150711, 2018). "However, a targeted shRNA library screen identified EIF5A, AMD1, SRM, and DHS as tumor suppressors in the Eμ-MYC model." (PMID 29799508, 2018). "MYC controls several functions in cancer cells, such as inducing DNA replication, regulating splicing factors, activating ribosome biogenesis, and protein synthesis, and it is involved in tumor immune escape." (PMID 29783691, 2018). "c-MYC oncogene can also account for lncRNA regulation in tumor cells." (PMID 29739426, 2018). "Moreover, Notch signaling can directly activate MYC, and a protooncogene holds a central role in regulating tumor growth." (PMID 29360267, 2018).
tumor (continued). "In addition, we found that PDEF promoted tumour proliferation and upregulated MYC-mediated gene transcription by promoting MAD1 degradation." (PMID 30217192, 2018). "Importantly, it was shown a major role for MYC in re-programming the tumor microenvironment, particularly for that concerns the inflammatory and immune components of tumor stroma." (PMID 30060526, 2018). "At the initial stage of tumorigenesis, these mutated genes might be tumor-initiating SNVs in conjunction with the CNAs of FAT1, MYC, PARP10, and CYC1." (PMID 30143682, 2018). "Furthermore, immunohistochemistry staining of tumor tissues from the in vivo efficacy study showed that the combination therapy significantly reduced MYC levels." (PMID 29295989, 2018). "Hence, a trivial explanation for the decreased tumor growth in IL-12-LNP treated mice is that the therapy was reducing MYC levels." (PMID 30458889, 2018). "Given that c-MYC is a key transcription factor in the regulation of TAM biology, miR-26 family members may act as tumor suppressors by suppressing the c-MYC pathway and decrease TAMs in ESCC tissues." (PMID 29892301, 2018). "c-MYC is estimated to be dysregulated or overexpressed in approximately 70% of all human cancers and is responsible for mediating multiple pathways important in tumor cell survival." (PMID 30312328, 2018). "For example, agonists of FBW7 can promote degradation of c-MYC and cyclin E in the tumor cells." (PMID 29415985, 2018). "Furthermore, we demonstrate that the MYC-driven epigenetic reprogramming favors the formation and maintenance of tumor-initiating cells endowed with metastatic capacity." (PMID 29523784, 2018). "The Eμ‐MYC mice developed mainly immature B220+CD19+IgM− tumours." (PMID 29498802, 2018). "Importantly, USP28 is highly expressed in colon cancers, making it a potential pharmacological target to control c-MYC-driving tumor cells." (PMID 29415985, 2018). "As recent studies showed that HDAC inhibitors act in cooperation with PI3K and mTOR inhibitors to inhibit tumor growth in MYC-driven tumors, we tested the HDAC class I inhibitor entinostat (MS-275) at a concentration ineffective for HDAC8 (500 nM) and combined it with the PI3K or mTOR inhibitor." (PMID 29515255, 2018). "Additionally, considering BRD4 linkage to MYC has been demonstrated in multiple disease settings, we examined the anti-tumor activity of AZD5153 in a MYC amplified (but also with BRD4 copy-number gain of 3) ovarian patient-derived xenograft, OV0452F." (PMID 30036377, 2018). "Synthetic lethality with spliceosome inhibition could provide a means to treat the many tumours with elevated c-MYC." (PMID 29796170, 2018). "Accompanying MYC suppression we found significantly reduced tumor cell proliferation." (PMID 30453475, 2018). "The proto-oncogene MYC controls a wide range of cellular processes, including cell proliferation, metabolism, cellular differentiation and genomic instability, and is a dominant driver of tumor transformation and progression." (PMID 28748451, 2018). "The DH-My6 cell line was generated from tumor tissue of a patient with MYC/BCL6 DHL." (PMID 30323893, 2018). "MYC protein abundance in cells treated with double treatment was synergistically lower than with either single agent, leading to an enhanced inhibitory effect on tumor cell proliferation, tumor growth, and tumor cell invasion." (PMID 30459933, 2018). "In rhabdoid tumor‐derived cells reintroduction of INI1 appears to suppress MYC functions." (PMID 30222246, 2018). "The oncogene MYC mRNA is up-regulated in tumor compared to normal." (PMID 30150711, 2018). "The ability of CXCL12 and MYC to promote cell migration by increasing glycolytic flux may also explain why CXCL12/CXCR452 and MYC53 are associated with increased tumor invasiveness and poor survival." (PMID 30202007, 2018).
tumor (continued). "Indeed, the treatment of tumor‐bearing mice for 4 days with another pan‐FGFR inhibitor, BGJ398, which inhibited PDX tumor growth, decreased both MYC and FGFR3 levels in the tumors." (PMID 29463565, 2018). "Expectedly, compared to their efficacy as single agents, Vismodegib and BEZ235 combined together, or individually combined with cisplatin significantly (p<0.01) delayed tumor growth over a 3-week period, suggesting that combinations have potency to inhibit MYC-driven MB proliferation in vivo." (PMID 29682173, 2018). "In addition, MYC expression has been suggested to be essential to reactivate the ESC-like program and to be the main cause of tumor malignancy." (PMID 30510261, 2018). "Our data predicts that in the presence of active MYC, loss of either NF2 or YAP activity may reduce the growth potential of the transformed structures and, speculatively, result in desired therapeutic effects on tumour cells with high MYC activity." (PMID 29507319, 2018). "In tumor cells, Nrf2 is usually activated by ROS-induced oncogenes, such as KRAS and c-MYC, and inhibition of its activity may contribute to the apoptosis of tumor cells and abrogated tumor growth." (PMID 30538633, 2018). "Interestingly, targeted drug screening, showed that high MYC-expressing SCLCs are vulnerable to Aurora kinase inhibition, which, combined with chemotherapy, strongly suppresses tumor progression." (PMID 30060526, 2018). "We suggest that the results and RGC‐based prognostic model developed in the present study probably reflect the essential pathobiological processes in early‐stage MYC‐driven malignization in AT liver cells, which consequently affect tumor progression and poor OS of HCC patients." (PMID 29117471, 2018). "Importantly, MYCMI-6 was not cytotoxic to primary normal human fibroblasts at concentrations that killed almost 100% of MYC-dependent tumor cells, thus demonstrating a promising therapeutic window for MYCMI-6." (PMID 29968736, 2018). "Overall, this in-silico results on MYC targets appear to suggest that MYC targets are positively associated with higher SUV levels, although experimental confirmation would be required for specific tumor types." (PMID 29349517, 2018). "This classification divides CRC into four subtypes: MSI immune with MSI, BRAF mutated, and CIMP positive tumours; canonical with WNT and MYC activation; metabolic with KRAS mutated tumours; and mesenchymal, characterized by stromal infiltration and TGF-β activation." (PMID 30188916, 2018). "JQ1 could still inhibit MYC or MYCN levels after 24 or 72 h in both genetically engineered GTML2 tumor cells and in MYC-amplified MB002 cells." (PMID 29511348, 2018). "However, it is remarkable that the only MYC amplified AFX case showed the highest tumor thickness (17.5 mm) of all cases (17.5 mm vs. median 3.25 mm, range 1.45 to 17.5)." (PMID 29765529, 2018). "None of the evaluated clinicopathological parameters (tumor invasion thickness, preexisting diseases/malignancies, smoking behavior, location, age, gender) were associated with MYC amplification (data not shown)." (PMID 29765529, 2018). "We next addressed the question whether cellular responses to MYCMI-6 treatment differentiate between MYC-dependent tumor cells and normal primary human cells." (PMID 29968736, 2018). "Since OIP5-AS1 is expressed at high level in undifferentiated tumor cells, we asked the question whether the promoter of OIP5-AS1 gene has possible binding motifs for stemness associated TFs (Yamanaka factors) MYC, KLF4, OCT4, SOX2, and NANOG." (PMID 29728583, 2018). "We did not observe any association between MYC amplification and tumor grade, tumor size, or age at diagnosis similar to other studies." (PMID 29523126, 2018).
tumor (continued). "Besides driving tumor initiation and progression, it is also well known that MYC is essential for tumor maintenance, malignant cells becoming addicted to continuous MYC overexpression." (PMID 30575780, 2018). "To verify our hypothesis that metformin inhibits tumor angiogenesis by suppressing JAK/STAT3/c-MYC signaling pathway, we detected the expression levels of related genes and proteins in tumor specimens from mice." (PMID 29088816, 2017). "Additionally, ARV-771 was shown to induce BRD4 and c-MYC degradation in 22Rv1 tumour xenografts in mice, and more importantly led to tumour regression in the 22Rv1 model following daily subcutaneous dosing of 30 mg/kg." (PMID 28298557, 2017). "Thus, our findings are consistent with a tumour‐suppressive role of HUWE1 in destabilising MYC post‐translationally." (PMID 28003334, 2017). "This suggests that cell-autonomous and non cell-autonomous apoptosis dependent on MYC upregulation may shape tumour growth in different ways, soliciting the need to reconsider the role of cell death in cancer in the light of this new level of complexity." (PMID 28420161, 2017). "MYC genes often emerge as late events in tumor progression and at tumor recurrence." (PMID 28333115, 2017). "Our data suggest that MYC overexpression compensates for lack of HIF-1 activity in hypoxic SCLC and that targeting regulatory steps in the glutaminolysis and lipogenesis pathways might be novel strategies to eradicate MYC amplified tumor cells." (PMID 28430666, 2017). "Whether MYC is also required for tumor maintenance and whether tumor cells become addicted to MYC was previously unclear." (PMID 28152508, 2017). "This multi-factorial concept has been strongly supported by a number of studies demonstrating further driver mutations and epigenetic changes, that play important roles in tumor proliferation, maintenance and abrogating checkpoints in the face of MYC overexpression." (PMID 29132323, 2017). "In fact, treating MYC-overexpressing TNBC with an inhibitor of CPT1A was effective in decreasing energy metabolism in MYC-overexpressing TNBC cells and in blocking tumor growth in a MYC-driven transgenic TNBC model as well as in a MYC-overexpressing patient-derived xenograft." (PMID 28412757, 2017). "Besides, a significant inverse correlation was found between the relative MYC expression in tumor tissues compared with their corresponding ANCTs and disease stage." (PMID 28480695, 2017). "Therefore, we also performed c-MYC immunohistochemistry which showed strong protein expression in >40% of tumor cells." (PMID 29187222, 2017). "Together, our data suggest that CDK9 inhibitors may have single-agent anti-tumour activity against a subset of SCLC that either carry c-MYC amplification or are MCL-1-addicted." (PMID 28714472, 2017). "To determine whether loss of DNMT3B function affects tumor cell proliferation and viability we carried out shRNA-mediated knock-down as well as pharmacologic inhibition of DNMT3B in MYC-driven T-ALL cells." (PMID 29100357, 2017). "Because c-MYC drives proliferation of many tumor cells including RMS, it is tempting to speculate that the increased c-MYC levels in ARMS LEF1 KD cells are responsible for induction of proliferation." (PMID 27965462, 2017). "Finally, MYC influences the tumor microenvironment, including the activation of angiogenesis and suppression of the host immune response." (PMID 28333115, 2017). "Therefore, we conclude that the signature based on these transcripts is a reliable for identifying tumor subtypes based on their c‐MYC status." (PMID 28275007, 2017).